RAD51 (RAD51 recombinase)
Diseases named in the same sentence as RAD51 in open-access papers (continued):
Sharing a sentence is not in itself a finding about the gene and the disease.
breast cancer (continued). "This property has been suggested to have important implications for acquisition of chemoresistance; the breast cancer tumor suppressor BRCA1 promotes HDR by mediating DNA end resection and RAD51 loading." (PMID 29475976, 2018). "Interestingly, five samples had no visible RAD51-foci prior to hyperthermia, suggesting that ~10% of the bladder tumors are inherently HR-deficient, a percentage similar to that previously reported for primary breast cancers." (PMID 30550547, 2018). "It is also known that miR-96 targets RAD51 and REV1, and that the overexpression of this miRNA in breast cancer in in vitro models results in improved sensitivity to PARP inhibitors." (PMID 30234015, 2018). "For instance, in breast cancer, raised levels of PRC2 leads to high levels H3K27 methylation in the promoter regions of FOXC1, E-cadherin, RAD51, RUNX3 and CDKN1C (p57kip2)." (PMID 27845897, 2017). "RAD51 forms a complex BRCA2 (breast cancer 2), which becomes activated by phosphorylation after DSB, enabling the binding of RAD51 to ssDNA." (PMID 26784176, 2016). "Our data further suggests that IGF-1R inhibition suppresses HR by downregulation of RAD51, and that this allows a strong antitumor activity in combination with PARP inhibitors in BRCA1 wild-type (HR proficient) ovarian and breast cancer cells." (PMID 26510816, 2015). "An early study conducted in Japanese hereditary breast cancer patients found 2 out of 45 patients contained a RAD51–R150Q variant that is absent among 200 sporadic breast cancer or 100 colon cancer cases, which suggested this site could be a disease-associated mutation." (PMID 25539919, 2015). "Using ovarian and breast cancer cellular models with known BRCA1 status, we evaluated their HR functionality by RAD51 foci formation assay." (PMID 26510816, 2015). "Our results (based on PCR analysis and inhibition of cell growth) highlighted three specific mediators, namely CDC20, RAD51, and CHEK1, as therapeutic targets in breast cancer cells." (PMID 25763370, 2015). "We next investigated RAD51 mRNA expression and correlation with histopathological parameters in the METABRIC (Molecular Taxonomy of Breast Cancer International Consortium) dataset." (PMID 24811120, 2014). "While little is known about the DDR in canine mammary cancer, comparable BRCA2 and Rad51 misregulations, point towards a high possibility of similarly altered HR pathway in the two species." (PMID 24641873, 2014). "Huang and co-workers identified B02 as a specific inhibitor of human RAD51 recombinase and demonstrated that B02 blocks HR repair in human embryonic kidney (HEK) and breast cancer cells and increases their sensitivity to a wide range of DNA damaging agents." (PMID 25401086, 2014). "In canine mammary carcinomas, BRCA2 and RAD51 show similar regulations, which indicates similar functions." (PMID 24641873, 2014). "This strongly suggests that this VUS is of high clinical significance and impact breast cancer by negatively affecting the interaction between BRCA2 and RAD51." (PMID 23704879, 2013). "It suggested that expressions for both XRCC3 and RAD51 were significantly higher in breast cancer (XRCC3: P<0.001; RAD51: P<0.001)." (PMID 23977219, 2013). "Thus, the data presented here could perhaps have clinical implications in that RAD51 and RPA might be useful diagnostic markers for pre-malignant (DCIS) breast cancers and, in particular, for screening breast cancers for mutations in the BRCA1 BRCT domain that result in hyper-recombination." (PMID 21666281, 2011). "We assessed the effect of the DNA repair proteins known as X-ray complementing protein 3 (XRCC3) and RAD51, to the invasive behavior of the MCF-7 luminal epithelial-like and BT20 basal-like triple negative human breast cancer cell lines." (PMID 21283680, 2011).
breast cancer (continued). "Although other noncoding variation in the RAD51 gene may be involved in BRCA1/2-mutation-negative breast cancers, the absence of coding or untranslated region mutations in this set of well-characterised familial cases implies that RAD51 is not a major familial breast cancer predisposition gene." (PMID 16762046, 2006). "Consistent with studies in several other tumour entities, including breast cancer and pancreatic ADC, our results demonstrate that Rad51 is overexpressed in tumour cell nuclei in NSCLC compared to normal tissues." (PMID 15956972, 2005). "We investigate allelic losses in microsatellites of the RAD51, RAD52, RAD54, BRCA1 and BRCA2 regions, and their correlations with nine pathologic parameters in 127 breast carcinomas." (PMID 10507777, 1999). "Currently, a first-in-class RAD51 inhibitor, CYT-0851, is undergoing a Phase I/II clinical trial (NCT03997968), recruiting patients with refractory B-cell malignancies and solid tumors, including breast cancer." (PMID 40949156, 2025). "Additionally, we found that the expression of p‐RPA32 and formation of RAD51 foci, two markers of HRR, was reduced in BCKDK‐silenced breast cancer cells, while the expression of the Ku70 and formation of 53BP1 foci, two markers of NHEJ, remained unaffected." (PMID 40298908, 2025). "IVA treatment led to significant reduction of RAD51-EGFP signals in all 5 breast cancer cell lines that overexpressed HCN2 or HCN3, but not in HEK293." (PMID 40764992, 2025). "To evaluate the potential clinical significance of the BCKDK‐mediated regulatory pathway in patient samples, we first assessed the levels of BCKDK, p‐RNF8S157, and RAD51 in 14 paired breast cancer lesions and adjacent noncancerous tissue samples." (PMID 40298908, 2025). "In response to DNA damage caused by ionizing radiation (IR), overexpression of KILR, but not KCTD1-5 inhibited RPA and RAD51 recruitment to DSBs in breast cancer cells." (PMID 38745269, 2024). "The basal level of the RAD51 foci score in untreated FFPE tumor samples has been previously advocated as a marker of functional HR and shown to predict olaparib response in breast cancer PDXs and, more recently, to predict response to platinum-based neoadjuvant therapy in a retrospective study." (PMID 38989145, 2024). "We obtained analogous results using the BRCA2-deficient (Brca2-/-) mouse mammary tumor cell line KB2P (clone 1.2129), confirming that treatment with IFNβ did not restore RAD51 foci." (PMID 37783689, 2023). "The RAD51 assay has recently proved feasible in routine FFPE tumor tissues, particularly in selecting patients with breast cancer who may be responsive to PARPi." (PMID 36836518, 2023). "Moreover, next-generation sequencing revealed that beyond BRCA1/2, mutations in homologous recombination effectors, such as PALB2, RAD51, ATM, BRIP1, BARD1, and CHEK2 also occur in breast cancer." (PMID 36613148, 2023). "Recently, detection of RAD51, a central HR protein, in immunostained formalin-fixed, paraffin-embedded (FFPE) sections without externally induced DNA damage has shown great promise in identifying HRD breast cancers." (PMID 36805632, 2023). "Genetic variability in DNA double-strand break repair genes such as RAD51 gene and its paralogs XRCC2、XRCC3 may contribute to the occurrence and progression of breast cancer." (PMID 36761956, 2023). "Elevated RAD51 expression also correlated with poor overall survival in two different datasets of EAC (GSE13898; cutoff: 6.237) and TCGA (cutoff: 363.63) as well as in colon (cutoff: 261) and breast cancer (cutoff: 6.31)." (PMID 36428789, 2022).
breast cancer (continued). "Breast cancer 1 (BRCA1) and breast cancer 2 (BRCA2) play an important role in the HR repair pathway by interacting with other DNA repair proteins such as Fanconi anemia (FA) proteins, ATM, RAD51, PALB2, MRE11A, RAD50, and NBN." (PMID 35785170, 2022). "Cpd1 is the only RAD51 inhibitor that specifically blocks D-loop formation during HR but not ssDNA binding, filament formation, or fork reversal by RAD51 in the concentration range up to the IC50 values determined for breast cancer cell lines in our study." (PMID 34356606, 2021). "RAD51 has been reported to maintain metastasis in triple-negative breast cancer, and RAD51 inhibition sensitizes breast cancer stem cells to PARP inhibitor." (PMID 31889908, 2019). "Based on these data, RAD51 could be a biomarker for aggressive TNBC and for racial disparity in breast cancer." (PMID 31492187, 2019). "Using two independent breast cancer patient‐derived tumor xenograft (PDX) panels, we assessed the antitumor activity of three PARPi and showed the potential of an immunostaining assay of the HRR protein RAD51 to predict PARPi sensitivity." (PMID 30377213, 2018). "Cells that lack Rad51C, a Rad51 paralog, are reported to be highly sensitive to olaparib, and two murine breast cancer models have revealed that a pan-Class I PI3K inhibitor, BKM120, has the ability to inhibit Rad51, which was shown to lead to an increase in the anti-tumor effect of olaparib." (PMID 29152062, 2017). "Interestingly, most of these key repair genes, including BRCA1, RAD51, RAD54L and BLM, were also identified in this study as E2F1 targets in breast cancer." (PMID 27666291, 2016). "Our results suggest that RAD51, XRCC3, and XRCC2 do not substantially contribute to breast cancer predisposition in the Finnish population." (PMID 25918678, 2015). "We tested this hypothesis in the mammary carcinoma cell line MCF7, which displays relatively high levels of spontaneous RAD51 foci." (PMID 25765654, 2015). "Immunohistochemistry was used to detect protein expressions of XRCC3 and RAD51 in 248 cases of breast cancer tissue and 78 cases of adjacent non-cancerous tissue." (PMID 23977219, 2013). "The results of our meta-analysis supported the negative association between RAD51 135G>C polymorphisms and AML, breast cancer, and ovarian cancer." (PMID 24040396, 2013). "As the roles of XRCC3 and RAD51 on cellular invasiveness are unknown, we explored the phenotypic effect resulting in the over-expression of XRCC3 and RAD51 on different breast cancer cell lines, vis-^-vis invasiveness." (PMID 21283680, 2011). "In breast cancer (BC), METTL3 knockdown significantly increases chemosensitivity to doxorubicin via modulation of the EGF/RAD51 signaling axis." (PMID 40406121, 2025). "We generated and characterized a transgenic mouse model (K14-Cre;Brca1fl/fl;Wwoxfl/fl) and observed that mice lacking both WWOX and BRCA1 developed basal-like mammary tumors and exhibited a decrease in 53BP1 foci and an increase in RAD51 foci, suggesting impaired DSB repair." (PMID 38499540, 2024). "The cut-off value of 10% RAD51+ geminin+ cells (that is, fHR score 10.0) was chosen to define fHRD versus fHRP in chemo-naïve specimens; this value was recently determined to be highly predictive of HRD in a cohort of >100 breast cancer patients, as assessed by PDX-based PARPi sensitivity." (PMID 36805632, 2023). "In this study, we evaluated both RAD51 and pRPA32 (a marker of DNA end resection, a distinct step involved in the initiation of HR activity) and demonstrate that the levels of both these proteins are high in EAC (OE19, FLO-1), colon cancer (HCT116, HT29) and breast cancer (MCF7) and cell lines." (PMID 36428789, 2022). "Moreover, the knockdown of RAD51, BRCA1 (breast cancer 1), and the RAD51 paralog XRCC3 (X-ray repair cross complementing 3) prevented the repair of the O6mG-induced DSBs leading to cell sensitization, while RAD51-CRISPR activation led to TMZ resistance." (PMID 35626024, 2022).
breast cancer (continued). "Although dysregulated (elevated) RAD51 could impact growth of cancer cells through possible impact on cell cycle, no changes in cell cycle were detected following overexpression of RAD51 in normal (HDF) or a breast cancer cell line tested." (PMID 36428789, 2022). "Furthermore, we also evaluated whether there is any positive correlation between RAD51 and CHEK1 expressions in breast cancer." (PMID 31492187, 2019). "In addition, a study using a breast cancer cell line showed that high intracellular levels of Akt repressed nuclear translocation of breast cancer susceptibility 1 (BRCA1) and Rad51, resulting in the lack of homologous recombination of DNA DSB repair." (PMID 30521029, 2019). "To assess the ability of the RAD51 assay to identify HRR‐deficient tumors beyond gBRCA mutations, we scored for RAD51 in 23 FFPE tumor samples from a cohort of patients with clinical suspicion of hereditary breast cancer and without gBRCA mutations." (PMID 30377213, 2018). "We evaluated the activity of the PARPi olaparib in patient‐derived tumor xenografts (PDXs) from breast cancer (BC) patients and investigated mechanisms of sensitivity through exome sequencing, BRCA1 promoter methylation analysis, and immunostaining of HRR proteins, including RAD51 nuclear foci." (PMID 30377213, 2018). "The selective repression of Rad51 by THL might be beneficial for tumor specific radiosensitization, because homologous recombination, but not nonhomologous end joining DNA repair, is abnormally elevated in breast cancer cell lines, including MCF-7 cells." (PMID 27525019, 2016). "Taken together these results indicate that RAD51 depletion suppressed the metastatic spread of MDA-MB-231 cells and RAD51 overexpression enhanced the metastatic spread of BT549 cells, suggesting that RAD51 increases the metastatic potential of breast cancer in vivo." (PMID 24811120, 2014). "Expression of XRCC3 and RAD51 in breast cancer and adjacent non-cancerous tissue." (PMID 23977219, 2013). "Based on the high expression of RAD51 and RPA relative to low M1775R expression, these results suggest that M1775R may promote excessive HRR in vivo as has been suggested to occur in some breast cancers with low BRCA1 levels." (PMID 21666281, 2011). "The level of autophagy in MCF7 breast cancer (BC) cells can be increased by mTOR inhibitor, rapamycin (RAPA), delayed the attendance of Rad51 and BRCA1 protein localization, and prolonged the expression of damage characteristic sensor γ-H2AX, resulted in the accumulation of DSB damage." (PMID 34321364, 2021). "Notably, CDK1, CCNA2, P4HA1, PAICS, and RAD51 showed a CERES score higher than zero in most breast cancer cell lines, indicating that they might not be essential to breast cancer." (PMID 34745136, 2021). "When breast cancer cells are treated with radiotherapy, chemotherapy or PARP inhibitors, the resulting DNA damage could be still repaired through the activation of specific DNA repair genes, such as ATM, BRCA1/2, RAD51, DNA-PK etc., thus cells survive and continue to proliferate." (PMID 30234015, 2018). "Additionally, single nucleotide primer extension analysis did not reveal any change in expression of RAD51 in LCLs from breast cancer patients, indicating that there is little, if any, allelic effect on RAD51 expression due to known or undetected genetic variation." (PMID 16762046, 2006). "Although the ER stress inducer TUN can induce ER stress and reduce RAD51, the effect of TUN is not specific for breast cancer cells only, and is thus unsuitable for use as a treatment regiment." (PMID 40764992, 2025).
breast cancer (continued). "While the RAD51 inhibitors synergized with WEE1 inhibition, no apparent synergistic effect was observed when combined with ATRi or DNA-PKi in MDA-MB-436 breast cancer cells." (PMID 35646698, 2022). "HspBP1-depleted U2OS cells, HspBP1-depleted breast cancer MCF-7 and MDA-MB-231 cells, and non-malignant MCF10A cells were tested for the ability to form IR-induced Rad51 foci." (PMID 35387978, 2022). "In conclusion, Olaparib-RAD51 inhibitor conjugates have the potential to break resistance mechanisms to Olaparib treatment in TNBC cells and sensitize breast cancer cells regardless of BRCAness." (PMID 34356606, 2021). "While it was not tested in ovarian cancer, in glioblastoma and breast cancers, it was demonstrated that knockdown of CHD4 decreases the expression of RAD51 and p21 that are tightly involved in cisplatin sensitivity." (PMID 34161330, 2021). "RAD51 was more highly expressed in Her2-positive and triple negative breast cancers (TNBC) than in the other types of breast cancers." (PMID 31506496, 2019). "The over-expressed CCNE1, CLGN, NEK2, PTTG1 and RAD51, and the under-expressed ADAMTS1, FOS, FOSB, IL6 and ZFP36 in tumor cells are examples of breast cancer genes without differential promoter methylation between normal and tumor samples." (PMID 25706888, 2015). "The mean percentage of positive cells was much higher in breast cancers than in adjacent non-cancerous tissues (XRCC3: 64% vs. 20%; RAD51: 83% vs. 55%)." (PMID 23977219, 2013). "Phenocopying the edited breast cancer cells, we found that TOPBP1 and RAD51 could not be efficiently deposited on damaged chromatin in sgRNA-1 and sgRNA-2 lung cancer cells." (PMID 38762174, 2024).